PDK1 (pyruvate dehydrogenase kinase 1)
Diseases named in the same sentence as PDK1 in open-access papers (continued):
Sharing a sentence is not in itself a finding about the gene and the disease.
ovarian carcinoma (continued). "In addition, PDK1 played regulatory roles in the metabolic switch and promoted cell adhesion, migration, invasion, angiogenesis, and anchorage-independent growth in ovarian cancer cells, leading to metastasis." (PMID 32071289, 2020). "To elucidate the mechanisms governing PDK1 upregulation in ovarian cancer cells, we first attempted to determine whether conditioned medium from CAFs regulates PDK1 expression in SKOV-3 and ES-2 cells." (PMID 32071289, 2020). "Moreover, the lack of IL-8 in A2780CP cells suggested that other downstream target(s) would be involved in PDK1-mediated effects in ovarian cancer." (PMID 32071289, 2020). "Importantly, higher PDK1 expression was correlated with shorter overall and disease-free survival, and PDK1 is an independent prognostic factor for overall survival, suggesting that PDK1 is a significant prognostic marker in ovarian cancer." (PMID 32071289, 2020). "We also elucidated the mechanisms by which COL11A1 promotes cancer cell sensitivity to anticancer drugs and we observed that, in ovarian cancer cells, chemoresistance developed via activation of the Akt/c/EBPβ pathway in concert with attenuated PDK1 ubiquitination and degradation." (PMID 30975980, 2019). "In this study, we used the ovarian cancer cell line SKOV3 as the model system and examined whether dicumarol (DIC), a coumarin compound, could inhibit ovarian cancer through targeting PDK1." (PMID 28617852, 2017). "Of note, previous reports showed that COL11A1 elevates phosphorylated Akt in ovarian cancer cells by stabilizing PDK1, and FLT4 participates in the induction of phosphorylation of extracellular signal-regulated kinase (ERK) 1/2 as well as in the proliferative and migratory ability of SG-2 cells." (PMID 28555007, 2017). "Considering that DIC potently inhibits the kinase activity of PDK1 both in a cell-free system and in ovarian cancer cells, we hypothesized that DIC would impact glucose metabolism and further the malignant behaviors of cancer cells." (PMID 28617852, 2017). "Collectively, these results indicate that PDK1 stabilization in chemoresistant ovarian cancer cells could be increased by COL11A1." (PMID 26087191, 2015). "Here, we further showed that COL11A1 could increase phosphorylated Akt in chemoresistant ovarian cancer cells by stabilizing PDK1 protein." (PMID 26087191, 2015). "In the present study, we elucidated the mechanisms by which COL11A1 promotes cancer cell sensitivity to anticancer drugs, and we observed that, in ovarian cancer cells, chemoresistance developed via activation of the Akt/c/EBPβ pathway in concert with increased PDK1 degradation." (PMID 26087191, 2015). "Moreover, Akt, the most extensively studied downstream target of both ILK and PDK1, has also been shown to be overexpressed in ovarian carcinomas." (PMID 18349831, 2008). "On the basis of these observations, we hypothesised that the expression of PPARβ and its downstream target PDK1 will also change with the progression of ovarian carcinoma." (PMID 18349831, 2008). "However, whether S1PR1 can regulate aging through PDK1 in ovarian cancer cells and whether LATS1/2 and YAP are involved in this regulation has not been reported." (PMID 37828220, 2023). "In the present study, S1P could induce PDK1 expression in ovarian cancer cells." (PMID 37828220, 2023). "According to Lee's research, we speculate that the high expression of PDK1 in ovarian cancer results in the inhibition of PDC in tumor cells, which drives the switch to fatty acid oxidation, promotes the metastasis of cancer cells and accelerates the adverse prognosis of ovarian cancer." (PMID 33403023, 2021). "We therefore examined whether PDK1 knockdown affects invasiveness of ovarian cancer." (PMID 33403023, 2021).
ovarian carcinoma (continued). "In addition to cell adhesion, our functional studies involving manipulation of PDK1 expression in ovarian cancer cells demonstrated roles in promoting cell migration, invasion, and angiogenesis, which are critical steps for metastasis, especially in the peritoneal microenvironment." (PMID 32071289, 2020). "Importantly, a role for PDK1 in ovarian cancer progression has been recently demonstrated, where authors showed that normal ovaries show no significant levels of PDK1, but enhanced expression of PDK1 was observed in borderline and low- to high-grade ovarian tumors." (PMID 27551332, 2016). "Hence, like other cancers, PDK1 may be a preferred molecular target for sensitising ovarian cancer cells to chemotherapeutic agents." (PMID 18349831, 2008). "In ovarian cancer, CD8+ T cell infiltration is negatively correlated with PDK1 expression, whereas PDK1 expression shows a positive correlation with PD-L1 levels." (PMID 39897050, 2025). "In this study, we found that PDK1 interacts with BGN and positively regulates BGN expression by modulating BGN protein stability in ovarian cancer cells." (PMID 39578715, 2024). "In ovarian cancer cells, the inhibition of miR-1244 promotes proliferation and aerobic glycolysis (PKM2, HK2, and PDK1) and ROCK1 expression." (PMID 38338859, 2024). "Our results showed that, after S1PR1 knockdown in ovarian cancer cells, the expression of LATS1/2 was significantly increased, the level of phosphorylated YAP was increased, and the expression of PDK1 was significantly decreased." (PMID 37828220, 2023). "Further, they demonstrated that PDK1 regulated tumor-mesothelial adhesion, invasion, and angiogenesis via α5β1 integrin and JNK/IL-8 signaling pathways and eventually promoted ovarian cancer metastasis." (PMID 35961973, 2022). "The impacts of TRPM7 silencing on the levels of glycolysis-related HK2, PDK1 and oxidative phosphorylation (OXPHOS)-related IDH3B and UQCRC1, HIF-1α expression and AMPK phosphorylation were determined in ovarian cancer." (PMID 35101076, 2022). "To understand how TRPM7 modulated metabolic reprogramming in ovarian cancer, we analyzed the expression of TRPM7, glycolysis-related HK2, PDK1, and OXPHOS-related IDH3B and UQCRC1 in 60 ovarian cancer tissues by IHC." (PMID 35101076, 2022). "Our results showed that the positive rates of PDK1 and CA125 in cases of ovarian cancer were almost the same." (PMID 33403023, 2021). "However, the role of PDK1 in the occurrence and development of ovarian cancer remains unclear." (PMID 33403023, 2021). "In particular, it has been documented that GULP1 activates SMAD3 or inactivates AKT/PDK1 and MAPK in ovarian cancer cells, while it inhibits the nuclear translocation of NRF2 and subsequently reduces the expression of HMOX1 in bladder cancer cells." (PMID 34576193, 2021). "Nonetheless, in ovarian cancer cells, GULP1 showed inhibitory effects on their proliferation while inducing phospho-SMAD3 or reducing phosphorylation of AKT/PDK1 and MAPK." (PMID 34576193, 2021). "Although the correlation between CA125 level and disease characteristics is stronger than that of PDK1, PDK1 still exhibits excellent prognostic value, while CA125 does not, which also confirms the special role of metastasis in the prognosis of ovarian cancer." (PMID 33403023, 2021). "Here the authors show that p85β promotes AXL protein stability, which in turn activates p110 to induce PDK1/SGK3 signaling, and therapeutically, p85β-expressing ovarian cancer cells are sensitive to AXL inhibition." (PMID 32385243, 2020). "Here, we have demonstrated that PDK1 induces IL-8, an angiogenic CXC chemokine highly expressed in ovarian cancers and ascites." (PMID 32071289, 2020). "Given that PDK1 can be induced by HIF111,12, the link between PDK1 and HIF1 in ovarian cancer will be further investigated in future experiments." (PMID 32071289, 2020).
ovarian carcinoma (continued). "Here we report that p85β signals through its upstream kinase AXL, which in turn activates p110 to induce PDK1/SGK3 signaling, establishing the mechanistic basis for targeting AXL in PIK3R2-amplified ovarian cancer." (PMID 32385243, 2020). "Therapeutically, p85β expression renders ovarian cancer cells vulnerable to inhibitors of AXL, p110, or PDK1." (PMID 32385243, 2020). "Previously, we revealed that COL11A1 is an important factor in Akt regulation and chemoresistance in ovarian cancer via its activation of the Akt/COL11A1/c/EBP pathway and reduction of PDK1 degradation." (PMID 32194423, 2020). "Weather PDK1 can be phosphorylated by PGK1, leading to ovarian cancer tumorigeneses and metastasis will be examined in future studies." (PMID 32071289, 2020). "Here, we demonstrated high expression of the mitochondrial gatekeeping enzyme, pyruvate dehydrogenase kinase 1 (PDK1), in both clinical samples and cell lines of ovarian cancer." (PMID 32071289, 2020). "In the present study, we used the ovarian cancer cell lines SKOV3 and A2780 as the model system, assessed the effect of DIC on PDK1 activity, and investigated the anticancer activities of DIC both in vitro and in vivo." (PMID 28617852, 2017). "As expected, concurrent over-expression of PDK2 and PDK1 enhanced the phosphorylation of PDHE1α, abolished the sensitizing function of DCA and partially abrogated the lethal effect of DCA plus Met in ovarian cancer cells." (PMID 27449090, 2016). "Our experiments confirmed that both the PDK1 inhibitor UCN-01, and the PI3K inhibitor LY294002, effectively inhibited pAkt signalling in two different ovarian carcinoma cell lines, when used as single drugs and in combination with pertuzumab." (PMID 22085636, 2012). "In addition, PDK1 regulated chondrocyte apoptosis via the p38 MAPK pathway and ovarian cancer cell metastasis through the modulation of JNK signaling." (PMID 36077661, 2022). "Furthermore, TRPM7 silencing also decreased the relative levels of glycolysis-related HK2 and PDK1 expression as well as PKM2 nuclear translocation, but increased OXPHOS-related IDH3B and UQCRC1 expression in ovarian cancer cells and tissues." (PMID 35101076, 2022). "Here, by gene expression profiling and digital pathology-mediated quantification of in situ markers in tumors, we investigated effects of PDK1 silencing on growth, angiogenesis and metabolic features of tumor xenografts formed by highly glycolytic OC316 and OVCAR3 ovarian cancer cells." (PMID 33562444, 2021). "Furthermore, combining detection of PDK1 and CA125 can more effectively predict the prognosis of ovarian cancer patients as the optimal area under curve, 0.73." (PMID 33403023, 2021). "PDK1 expression was consistently upregulated in ovarian cancer, compared with nonmalignant human ovarian epithelial cell lines (HOSE)." (PMID 32071289, 2020). "Knockdown of PDK1 did not affect ovarian cancer cell proliferation, but retarded anchorage-independent growth." (PMID 32071289, 2020). "qPCR analyses additionally revealed significantly higher PDK1 mRNA levels in ovarian cancers relative to their corresponding non-tumor counterparts from 20 paired clinical samples (P < 0.05, lower right)." (PMID 32071289, 2020). "By inhibiting the kinase activity of PDK1, DIC initiates a cascade of alterations in multiple phenotypes of ovarian cancer SKOV3 and A2780 cells, including antagonizing the Warburg effect, increasing ROS production, and inducing apoptosis, which leads to effective inhibition of tumor growth in vivo." (PMID 28617852, 2017). "In this respect, the existence of activated and strongly expressed PDK1 protein in OVCAR3-sfRon cells with no expression of this protein in OVCAR3 cells clearly indicates a potential role for PDK1 in progression of ovarian cancers expressing sfRon." (PMID 27551332, 2016).
ovarian carcinoma (continued). "Indeed, CAMKK2 was shown to regulate the phosphorylation of Akt at both the threonine and serine residues in ovarian cancer cells, and combined downregulation of the CAMKK2 and PDK1 proteins had comparable effects on Akt phosphorylation, as did pharmacological inhibition of CAMKK2 and PI3K." (PMID 29064423, 2017). "On the other hand, the lack of PDK1 expression in normal ovaries, its weak expression in benign tumours and its elevated expression in pre-malignant and low- to high-grade ovarian carcinomas provide compelling evidence of its oncogeneic role in ovarian cancer progression." (PMID 18349831, 2008).
melanoma (50 papers, 2010 to 2025). A malignant, usually aggressive tumor composed of atypical, neoplastic melanocytes. "Our analysis of clinical samples showed that high expression of Ku80 and PDK1 was associated with poor prognosis in melanoma patients." (PMID 31023624, 2019). "Mechanistically, Ku80 bound to the promoter of PDK1 to enhance its transcription, and overexpression of PDK1 partially reversed the growth inhibition caused by Ku80 knockdown in melanoma cells and mouse xenograft models." (PMID 31023624, 2019). "In melanoma, PDK1 has been implicated in disease development and progression through regulation of Akt, SGK3 and FOXO3a." (PMID 30622697, 2019). "Metastatic melanoma is associated with increased PDK1 expression." (PMID 34768921, 2021). "Inhibiting PDK1 caused BRAFV600E inhibitor-resistant melanoma regression." (PMID 31285545, 2020). "Finally, the ability of NK cell to suppress the metastasis of B16 melanoma exhibited severer in the PDK1 and Rictor double-deficient mice than that in RictorKO or PDK1KO mice." (PMID 33633735, 2020). "Finally, our clinical data indicated that the expression of Ku80 and PDK1 were positively correlated in melanoma tissues, and their elevated expression was associated with poor prognosis in melanoma patients." (PMID 31023624, 2019). "To test this hypothesis, we investigated whether overexpression of PDK1 could rescue the inhibitory effects caused by Ku80 knockdown in melanoma cells." (PMID 31023624, 2019). "Moreover, we examined the binding of Ku80 at the endogenous promoter of PDK1 by ChIP, and confirmed that Ku80 had increased association with the PDK1 promoter in melanoma cells." (PMID 31023624, 2019). "Furthermore, Ku80 and PDK1 were highly expressed in melanoma tissues, and associated with poor prognosis in melanoma patients." (PMID 31023624, 2019). "Together, these findings validate the biological relevance of the added proteins, namely PIM1, MEK1, CDK2, and PDK1, in the central pathways of melanoma." (PMID 40649898, 2025). "Through pathway enrichment analysis, four key melanoma-associated genes (PIM1, MEK1, CDK2, and PDK1) were identified as potential therapeutic targets." (PMID 40649898, 2025). "Depleting PDK1 also led to the regression of established melanomas and eliminated melanoma subpopulations that were resistant to targeted BRAF inhibition." (PMID 37649668, 2023). "In melanoma, PDK1 was revealed to facilitate resistance of targeted BRAF inhibition through mediating oncogene-induced senescence induced by BRAFV600E." (PMID 35961973, 2022). "Ku80 was a potential molecular target for melanoma treatment and regulated anti-tumor role of melatonin by targeting and activating PDK1 in HIF1A-dependent manner." (PMID 33962616, 2021). "Taken together, suppression of the ARNT/PDK1 axis promotes melanoma metastasis through increased ROS production." (PMID 33446631, 2021). "It is worth noting that in clinical databases, PDK1 expression was negatively correlated with melanoma as compared with nevi." (PMID 33446631, 2021). "Our analysis revealed that the expression of Ku80 was significantly elevated in melanoma tissues, and the protein levels of PDK1 and Ku80 were positively correlated in melanoma samples." (PMID 31023624, 2019). "To further demonstrate that PDK1 mediated Ku80-regulated melanoma growth in vivo, we established a melanoma xenograft mouse model." (PMID 31023624, 2019). "The constitutive activity of STAT3 in melanoma contributes to increase the expression level of PDK1 which, in turn phosphorylate and activate AGC kinases including Akt, PKC, and SGK." (PMID 30622697, 2019).
melanoma (continued). "Previous studies described that increased levels of c-Jun in melanoma cell lines coincide with upregulation of phosphoinositide-dependent kinase 1 (PDK1) and phosphorylation of protein kinase C (PKC) and AKT32." (PMID 31378787, 2019). "In the current study, we established that STAT3 is constitutively bound to the PDK1 promoter and promotes PDK1 transcription in melanoma through at least two STAT3 responsive elements." (PMID 30622697, 2019). "To uncover the clinical significance of Ku80 and further confirm its relevance with PDK1, we detected their expression by immunohistochemical (IHC) staining in a tissue microarray that contained 99 melanoma samples and 8 normal samples." (PMID 31023624, 2019). "Xenografts into nude mice of melanoma cells with PDK1 downregulation displayed reduced growth compared with control cells." (PMID 31454998, 2019). "Our results also established that PDK1 is an important mediator of drug-resistance mediated by STAT3 in melanoma." (PMID 30622697, 2019). "PDK1 is an important metabolic enzyme in aerobic glycolysis, and highly expressed in many tumors including melanoma." (PMID 31023624, 2019). "Consistently, our results showed that the expression of Ku80 and PDK1 were positively correlated in melanoma tissues." (PMID 31023624, 2019). "Consistently, the protein level of PDK1 was increased in melanoma cells with Ku80 overexpression, which was reverted in part by knockdown of HIF1-α." (PMID 31023624, 2019). "Transduction of WM9 and UACC903 melanoma cells with STAT3-small hairpin RNA decreased both PDK1 mRNA and protein levels." (PMID 30622697, 2019). "Altogether, these experiments supported that PDK1 was involved in the Ku80-regulated melanoma growth." (PMID 31023624, 2019). "Western blot showed that Ku80 was specifically detected among the nuclear proteins bound at the PDK1 promoter, and it was more enriched in the nuclei of melanoma cells." (PMID 31023624, 2019). "Potentially relevant proteins include MEK1/2 (8% of melanomas), involved in the MAPK-pathway, and mTOR (10.4% of primary melanomas) or PDK1, involved in the PI3K-Akt-mTOR pathway." (PMID 30460579, 2018). "DCA has been tested in multiple cell culture and rodent models of cancer, and PDK1 knock-down has been described to enhance the sensitivity of BRAFV600E positive melanoma to BRAF inhibitors." (PMID 28595656, 2017). "PDK1 expression, activation, and subsequent stimulation of downstream substrates can also be regulated by c-Jun transcription factor contributing to melanoma growth." (PMID 28430130, 2017). "Following these studies, another group showed that SGK3 together with PDK1 are implicated in melanomas harbouring BRAF mutations and wild type PTEN, which in fact account for more than half the cases of melanomas occurrence." (PMID 29064423, 2017). "These authors also showed that inhibition of PI3K signaling effectively synergize with the PDK1 inhibitor, showing a novel therapeutic approach in melanoma treatment." (PMID 28430130, 2017). "We observed a decreased PDK1 activation in pre-malignant 4C cell line and in melanoma cell lines 4C11− and 4C11+ silenced for Timp1." (PMID 28430130, 2017). "During melanoma initiation, PDK1 is the intermediate for the PKC regulation by the tissue inhibitor of metalloproteinase-1 (TIMP1), and in later stages of progression and metastasis, it promotes resistance to anoikis." (PMID 29064423, 2017). "Studies have shown high levels of activated PDK1 in a large percentage of common tumor types, including melanoma, breast, lung, gastric, prostate, hematological, and ovarian cancers." (PMID 26684827, 2015). "Pinner and Sahai showed that a fine balance between PDK1 and Rnd3 expression is required for the amoeboid movement of melanoma cells, because the two proteins have opposing roles in controlling ROCK-I activity." (PMID 21209796, 2010).